TET2 (tet methylcytosine dioxygenase 2)
Diseases named in the same sentence as TET2 in open-access papers (continued):
Sharing a sentence is not in itself a finding about the gene and the disease.
tumor (continued). "WES identified numerous SNVs/indels in Tet2−/− tumours, indicating that TET2 loss constitutes a state of genetic mutagenicity." (PMID 28440315, 2017). "Our study also demonstrated that a significantly higher frequency of mutations occurred at loci with the gain of 5hmC in Tet2−/− tumours, where TET2 normally binds." (PMID 28440315, 2017). "Exome sequencing of Tet2−/− tumours and targeted single-cell exome sequencing of premalignant wild-type (WT) and Tet2−/− HSCs/HPCs show that TET2 loss leads to genomic hypermutability in HSCs/HPCs." (PMID 28440315, 2017). "For these two ATL patients, we PCR amplified the TET2 region overlapping these mutations and cloned and sequenced five clones for high tumor grade and matched samples." (PMID 26880370, 2016). "They concluded that TET2 was a novel bona fide tumor suppressor, noting that the majority of mutations are heterozygous (55%) and that TET2 defects precede the well-known JAK2 V617F driver mutation in MPN HSCs." (PMID 24622842, 2014). "Mechanistically, epithelial-mesenchymal transition (EMT) and the activation of the WNT pathway, which is normally recognized as tumor promotion events, were shown to correlate with the cytoplasm-nucleus shuttling of TET2, which is associated with tumor suppression." (PMID 41605908, 2026). "TET2 or DNMT3A deficiency in HSPCs may favor a distinctive tumor milieu, but the functional effects of their loss in the TME of AITL needsx further exploration." (PMID 40510016, 2025). "IL-4, in collaboration with IL-21, is also essential for germinal center B cells maturation; we recently reported the importance of the interaction between germinal center B cells bearing Tet2 mutations and tumor cells in the pathogenesis of AITL using a murine model." (PMID 40164718, 2025). "Notably, whereas DNA demethylation caused limited transcriptional changes, key tumour suppressor genes, including TET2, were upregulated in a methylation-dependent manner." (PMID 40611304, 2025). "Although the function of TET2 was unknown at this time, subsequent work has demonstrated a loss of function associated with TET2 mutation, indicating a role as a tumor suppressor and driver of hematological malignancy." (PMID 40116537, 2025). "Furthermore, the impact of TET2 mutations on non-tumor cells was assessed by calculating the ratio of VAFs between TET2 and RHOA mutations as an indicator of the expansion of TET2-mutated non-tumor cells." (PMID 40164718, 2025). "TET2 mutations were the strongest genetic predictor of TI-CH, enhanced monocyte migration to lung tumor cells, fuelled a myeloid-rich tumor microenvironment in mice, and resulted in the promotion of tumor organoid growth." (PMID 40267425, 2025). "Notably, infiltrating immune and tumor cells harbor TET2 mutations, possibly affecting the tumor microenvironment (TME) in AITL." (PMID 40164718, 2025). "This increase of more than 55% could also be classified as multi-hit TET2 mutations, which meant that a biallelic alteration due to loss of heterozygosity also reflected the increase of clonal tumor load." (PMID 40919141, 2025). "In this study, we revealed DNA damage, TET2 upregulation, demethylation, and re-expression of tumor suppressors on the underlying mechanism of DNMTi anticancer activity and resistance, particularly in the context of a lower dose (0.5 μM) of DNMTi, in the presence and absence of the DNMT1 gene." (PMID 39057134, 2024). "In addition, TET2 reduction and 5hmC levels were associated with high tumor grade, pathologic stage, metastasis, and vascular thrombosis in 130 ovarian carcinoma patients." (PMID 36979633, 2023). "As TET2 deficiency strongly activates mTORC1 and promotes tumor growth, we wondered whether Tet2 KO also affects growth of mice." (PMID 37550284, 2023).
tumor (continued). "Integration of SNP array, exome, and FISH data was used to infer tumor phylogeny, which indicated that disease pathogenesis was initiated by the TET2 nonsense mutation with subsequent deletion of the second TET2 allele, followed by acquisition of the NPM1 mutation." (PMID 36480300, 2023). "Similarly, Tet-2 deficiency in mice promoted tumor growth due to increased expansion of immunosuppressive granulocytic myeloid-derived suppressor cells (G-MDSCs)." (PMID 36672677, 2023). "This suggests a tumour suppressor role for TET2 in UV-exposed pDCs, and may explain the strong association between TET2 inactivation, skin localization and UV-associated mutations in BPDCN." (PMID 37286599, 2023). "WDR24 KO abolishes mTORC1 activation and tumor growth advantage induced by TET2 deficiency." (PMID 37550284, 2023). "However, TET2 or DNMT3A mutations alone have been shown to be insufficient for tumor formation, and additional mutations are required to further drive the clonal expansion." (PMID 38199781, 2023). "More importantly, the TET2 gene may be a predisposition gene for haematological malignancy, initiating the tumour with the second hits from other gene mutations." (PMID 35279121, 2022). "Notably, TET2 dysfunction mutations are generally associated with DNA hypermethylation, tumor progression, and poor patient outcomes." (PMID 35309925, 2022). "We aimed to compare the clinical characteristics of patients with germline and somatic TET2 mutations in haematological diseases and to analyse whether germline TET2 mutations have a family aggregation and tumour predisposition." (PMID 35279121, 2022). "Moreover, the TET2 gene has been described as a tumor-suppressor gene with its homozygous and heterozygous mutations leading to hematopoietic malignancies in humans." (PMID 34660059, 2021). "To investigate whether TET2/DNMT3A mutations were detectable in human tumor samples, we analyzed frequency of TET2 and DNMT3A mutations in a spectrum of over 100 cancer types." (PMID 34039392, 2021). "Notably, Tet2-deficient tumor infiltrating macrophages exhibit defective immunosuppressive capacity in a mouse melanoma model as a result of altered cytokine expression profile." (PMID 33520997, 2020). "Myeloid-specific Tet2 loss causes higher numbers of tumor-infiltrating T cells." (PMID 33184433, 2020). "In human myeloid malignancies, inactivating mutations of ASXL1 and TET2 often occur together in the same patient's malignant cells, suggesting that loss of these two tumor suppressors may act synergistically in myeloid transformation." (PMID 31064769, 2019). "In addition to DNMT3A, mutations in genes such as JAK2 and TET2, which are also located in hematopoietic clones, can confound the detection of tumor‐derived variants in blood." (PMID 30672098, 2019). "However, we observed hypermethylation at TET2/3 gene promoters with concomitant loss of 5hmC at the same CpGs and a corresponding reduction in TET2/3 expression in the tumour." (PMID 29263824, 2017). "Therefore, at least in these two patients, the identified TET2 mutation is specific to the tumor cell population." (PMID 28881727, 2017). "Interestingly, at variance with tumor cells often expressing reduced TET2 levels, increased TET2 expression was reported in tumor-associated macrophages." (PMID 29156643, 2017). "However, most studies on Tet2 loss-of-function mutations have focused on the tumor suppressor function of Tet2." (PMID 28408905, 2017). "Finally, direct sequencing of matched control and tumor samples revealed that TET2 mutation was present only in ATL tumor cells." (PMID 26880370, 2016).
tumor (continued). "In addition, TET2 expression in tumor tissues was significantly associated with lymph node metastasis among patients with ESCC (P = 0.040)." (PMID 27050164, 2016). "In addition to AML, TET2 mutations and/or deletions have been observed in other types of tumor, including bladder, breast, kidney, liver, lung and uterine cancers." (PMID 26869355, 2016). "Also upregulated is the oncogenic miR-22 that triggers EMT, inhibits the ten-eleven-translocation gene 2 (TET2) tumor suppressors, causing an enhanced hematopoietic stem cell self-renewal, transformation and metastasis." (PMID 26681200, 2015). "The majority of TET2 mutations recorded in patients with myeloid malignancy are within regions critical for enzymatic activity suggesting they are loss of function mutations and hence TET2 is seen to be having a tumour suppressor role." (PMID 25276435, 2014). "Two additional, arbitrarily chosen loci that showed age-related hypermethylation on the array, DDAH2, an epigenetic marker associated with cellular differentiation, and TET2, a putative tumor suppressor gene, also were substantially hypermethylated in old epidermis samples." (PMID 20523906, 2010). "Thus, TET2 mutations in myeloid cells can functionally impact tumor cell clonogenicity and growth." (PMID 40267425, 2025). "Currently, it is unclear whether TET2 is implicated in the re-expression of p16ink4A and p15ink4B tumor suppressors despite its widely recognized function of site-specific demethylation in mammalian cells and whether aza-T-dCyd demethylates tumor suppressor genes at low doses." (PMID 39057134, 2024). "Therefore, TET2-deficient tumor cells are more sensitive to mTORC1 inhibition." (PMID 37550284, 2023). "For example, TET2 is another tumor suppressor gene, mutations in which are thought to lead to hematopoietic stem cell proliferation deficiencies and may prevent genomic stability by impeding the addition of 5-hydroxymethylcytosine at sites of DNA damage in cancer cells." (PMID 38001699, 2023). "Unlike the increased phosphorylation of Ulk1, both LCI and LCII diminish dramatically in Tet2-deficient mouse livers, which is confirmed in TET2 KO tumor cells, suggesting that Tet2 might promote activation of autophagy in both mTORC1-dependent and -independent manners." (PMID 37550284, 2023). "Furthermore, premalignant cells with TET2 mutations may differentiate into not only T-lineage tumor cells but also B cells." (PMID 36428791, 2022). "Considering the updated 2016 WHO classification, the significant role of TET2 mutation in haematological neoplasms, and data from our previous research, we performed this study mainly to understand if germline TET2 mutation has a family aggregation phenomenon and is a tumour predisposition gene." (PMID 35279121, 2022). "Therefore, although we did not directly measure D-2HG levels, the partial inhibition of TET2 may explain the lower overall methylation in IDH1R132H-mutated tumours." (PMID 33740099, 2021). "Genotyping the tumour samples would assist in determining whether a polymorphism or variant in TET2 is the cause of downregulated TET2 levels, thereby further supporting previous findings regarding TET2 as a potential marker and driver of malignancy in NHL." (PMID 34899857, 2021). "Notably, TET2 is one of the tumor suppressor genes associated with ASM." (PMID 33246418, 2020). "Accordingly, loss of TET2 results in BRCAs reduction, impairs homologous recombination in DNA repair, and, if combined with DNA damaging chemotherapeutic agents, might sensitize tumor cells to PARPis." (PMID 31001476, 2019). "Thus, adequate vitamin C intake in the context of hereditary heterozygous TET2 loss-of-function mutations might reduce risk of neoplasia, a subject that needs further study." (PMID 30890702, 2019).
tumor (continued). "The participants with a) the SF3B1 p.K666N and b) SRSF2 p.P95L/TET2 p.I1873T variants, respectively, both had haematological malignancies diagnosed in a closer timeframe after blood draw (exact date unknown) and therefore, tumour cells may have been detected." (PMID 29641532, 2018). "Finally, it is worth noting that DNMT3A and TET2 mutations are also frequently observed in age-related clonal hematopoiesis, suggesting a central role of these two enzymes in age-related phenotypes and tumor development." (PMID 29069286, 2018). "TET1 promotes tumor growth by regulating genes involved in ribosomal biogenesis, while TET2 suppresses tumorigenesis." (PMID 40520993, 2025). "Three cases showed TET2 or IDH2 mutation in sorted cells that were undetected in the whole‐tissue section, likely due to low tumor content and sub‐clonal mutation." (PMID 40510016, 2025). "Using CITE-seq, the authors demonstrated that Tet2-null tumor-infiltrating macrophages produced increased levels of TGFβ, which activated the TGFβ pathway in tumor cells." (PMID 39874138, 2025). "Several genes encoding DNA methylation enzymes, including TET2 (ten-eleven translocation (TET) oncogene family member 2), which is a tumor suppressor, are mutated in AML." (PMID 41188771, 2025). "Alternatively, and in accordance with previous studies, TET2, DNMT3A, and TET3 were sometimes observed in the myeloid or B‐cell fraction in addition to the tumor indicating it was likely an early founding mutation that occurred in a progenitor cells." (PMID 40510016, 2025). "Lactate can upregulate the expression of SGK1 through demethylation mediated by TET2, enhancing the immunosuppressive function of MDSCs to promote tumor progression." (PMID 40917754, 2025). "Additional clinical validation using TMAs revealed that CCNY, TET2, and phosphorylated PRC1were significantly upregulated in tumor tissues." (PMID 40665337, 2025). "Tumor cells can upregulate DNMT3A or lose TET2 function, substituting DNA methylation for H3K27me3 marks to re-silence critical tumor suppressor genes and restore a malignant phenotype." (PMID 40032852, 2025). "Recurrent mutations in key epigenetic regulators such as EZH2, KMT2D, CREBBP, and TET2 lead to altered chromatin states, repression of tumor suppressor genes, and enhanced oncogenic signaling." (PMID 40943058, 2025). "First, significantly higher staining intensities of phosphorylated PRC1, CCNY, and TET2 were detected in tumor tissues compared to normal tissues." (PMID 40665337, 2025). "Recent research has highlighted the importance of TET2 in regulating the tumour microenvironment and immune evasion mechanisms." (PMID 41169875, 2025). "These CHIP-related mutations, particularly in genes such as DNMT3A, TET2, and ASXL1, can be inadvertently detected in plasma cfDNA and misattributed to the tumor, resulting in false-positive findings and erroneous clinical interpretations." (PMID 40869308, 2025). "Our results revealed that a subset of patients with a high VAF ratio of TET2 to RHOA mutations, possibly indicating the expansion of non-tumor cells carrying TET2-CH, had a significantly worse prognosis than the low-ratio group." (PMID 40164718, 2025). "Further experiments also showed an increase in migration velocity, together supporting the function of TET2 as a tumor suppressor gene in parathyroid tissues." (PMID 40116537, 2025). "WES of purified, neoplastic T‐cell (CD3+PD1+) demonstrated high concordance with whole tumor biopsies and validated the presence of TET2 and DNMT3A in tumor and non‐lymphoid cells, but other mutations (CD28, RHOAG17V, IDH2R172, PLCG1) in neoplastic cells." (PMID 40510016, 2025). "This highlights TET2’s oncogenic role in driving resistance and positions SCCs as potential tumor-initiating populations, making them promising therapeutic targets." (PMID 40196510, 2025).
tumor (continued). "This is achieved through the nuclear translocation of RAC1 and the subsequent transcriptional activation of the epigenetic modifier TET2 leading to increased levels of p21 and p27, which significantly influence tumour behaviour." (PMID 40715090, 2025). "The TET2 gene is a tumour suppressor located on chromosome 4q24 and is a member of the TET enzyme family." (PMID 41169875, 2025). "Expression of RHOA G17V encoded by the RHOA mutation and TET2 loss induces T‐cell lymphomas with features of AITL, and the proliferation of such tumor cells is dependent on the activation of inducible co‐stimulator/PI3K/mTOR signaling." (PMID 40599235, 2025). "TET2 (TET oncogene family member 2) is a candidate tumour suppressor gene located at chromosome 4q24, critical for maintaining the normal haematopoietic function through its role in DNA demethylation." (PMID 41031827, 2025). "This is consistent with other studies showing that both TET1 and TET2 expression leads to reduced tumor growth in xenograft mouse models." (PMID 40116537, 2025). "In tumours, it inhibits α-KG-dependent dioxygenases, such as TET2 and Jumonji-C demethylases, thereby altering DNA and histone methylation." (PMID 40750944, 2025). "For instance, studies have indicated that the stability of the TET2 protein in tumor cells is affected by the autophagy pathway." (PMID 39840982, 2025). "Deletion of TET2 in colon tumor cells reduces chemokine and PD‐L1 expression, as well as tumor lymphocyte infiltration, allowing tumors to evade antitumor immunity and resist anti‐PD‐L1 therapy." (PMID 40599235, 2025). "In conclusion, we revealed a novel target of SGK1 in the regulation of the immunosuppressive function of MDSCs by lactate, and clarified the important role of TET2-mediated SGK1 demethylation in anti-tumor immunity." (PMID 40917754, 2025). "Tet2-mutant monocytes preferentially migrated towards tumor cells and accumulated as macrophages within murine tumors." (PMID 40267425, 2025). "Mechanistically, elevated blood glucose levels impede AMPK‐mediated phosphorylation of TET proteins, which leads to destabilization of the tumor suppressor TET2 and a decrease in 5hmC levels." (PMID 40599235, 2025). "TET2 destabilization was induced by AMPK-mediated phosphorylation at Ser99 and the tumor suppressive function of TET2 was dysregulated." (PMID 40427015, 2025). "Targeting TET2, either alone or in combination with an ATM inhibitor, significantly suppressed tumor growth, highlighting TET2 as a promising therapeutic target." (PMID 40196510, 2025). "Restoration of TET2 can reconstruct the inflammatory transcription program and enhance anti-tumor immunity." (PMID 41394878, 2025). "The relationship between TET2 and personalized therapy is becoming increasingly significant, particularly with the increasing application of genomic profiling of tumours." (PMID 41169875, 2025). "In-depth profiling identified shared mutations in TET2 and DNMT3A (DNA methyltransferase 3 alpha) genes in both B and T cell tumours which suggested a common clonal origin, although molecular signatures later discerned two distinct malignancies." (PMID 40200078, 2025). "Surprisingly, several findings on therapeutic resistance also support the tumour-promoting role of TET2 97-99." (PMID 40860147, 2025). "Consistent with the clinical association between CHIP and a myeloid-rich lung tumor microenvironment, the percentage of Tet2-mutant cells in blood positively correlated with the overall myeloid infiltration in the tumor." (PMID 40267425, 2025). "2HG induces DNA hypermethylation by targeting TET2, mediating gene silencing and tumor progression in hematological malignancies." (PMID 40427015, 2025). "This relationship underscores the potential for developing drugs that not only target TET2 directly but also enhance its function within immune cells to improve anti-tumour immunity." (PMID 41169875, 2025).